CSTP1 (cystatin pseudogene 1)
Synonyms: dJ850N15.1
Gene: Transcribed unprocessed pseudogene on chromosome 20 (23,918,771 to 23,922,169, reverse strand). Ensembl gene ENSG00000228476.
Diseases named in the same sentence as CSTP1 in open-access papers:
CSTP1 is named in the same sentence as 5 diseases in open-access papers, as found by Europe PMC text mining. Sharing a sentence is not in itself a finding about the gene and the disease. The quoted sentences say what the papers report.
bladder (1 paper, 2013). "To investigate the role of CSTP1 in vivo, we established human bladder xenograft tumors in nude mice by injection of control EJ cells or EJ cells stably expressing either wild type CSTP1 or CSTP1 ΔPP2Ac." (PMID 23799035, 2013). "Overexpression of CSTP1 inhibited bladder cancer cell proliferation, colony formation in vitro and bladder xenograft tumor growth in nude mice." (PMID 23799035, 2013).
bladder cancers (1 paper, 2013). "Kaplan-Meier curves revealed that decreased expression of CSTP1 implicated significantly reduced recurrence-free survival in patients suffered from non-invasive bladder cancers." (PMID 23799035, 2013). "Since CSTP1 is downregulated in bladder cancer tissues, so we asked whether loss of CSTP1 expression in urothelial cells could result in the activation of Akt kinase and inactivation of FOXO factor." (PMID 23799035, 2013). "Because of the limited data acquired from muscle invasive patients, the effects of the decreased expression of CSTP1 on the clinical outcomes were examined only in non-invasive bladder cancer patients." (PMID 23799035, 2013). "the effects of CSTP1 on bladder cancer cell cycle, apoptosis and tumor formation in vivo and the underlined molecular mechanisms; ii." (PMID 23799035, 2013). "Consistent with this knowledge, our study showed that the expression of CSTP1 mRNA dramatically decreased in 80% of bladder cancer tissues." (PMID 23799035, 2013). "To explore the underlined mechanisms responsible for the elevated apoptosis and retarded cell cycle of bladder cancer cells mediated by CSTP1, we seek to find signaling pathways downstream of CSTP1 overexpression." (PMID 23799035, 2013). "the significance of decreased expression of CSTP1 on the recurrence and prognosis of non-invasive bladder cancers." (PMID 23799035, 2013). "CSTP1 was stably overexpressed in EJ bladder cancer cells via lentiviral infection and cell proliferation was assessed by MTT method." (PMID 23799035, 2013). "Expression profile analysis showed that CSTP1 expression is selectively down-regulated in non-invasive bladder cancer tissues and over-expression of CSTP1 suppressed the size of tumors in nude mice." (PMID 23799035, 2013). "A more prevalent decrease of CSTP1 expression was found in non-invasive bladder cancer tissues than that in the muscle-invasive tissues, provides a new strong evidence to this point of view." (PMID 23799035, 2013). "This suggests that protein phosphatase CSTP1 could function as a tumor suppressor, at least, in human bladder cancers." (PMID 23799035, 2013). "Furthermore, two sets of microarray dataset obtained from Oncomine also revealed that CSTP1 mRNA expression decreased in bladder cancers, with p-values of 0.005(up) and 2.62E-4(down) respectively." (PMID 23799035, 2013). "In our study, expression levels of CSTP1 are positively correlated to the recurrence-free survival of patients with Ta and T1 bladder cancers, indicate it may be a useful marker for prognostic prediction of non-muscle invasive bladder cancers." (PMID 23799035, 2013). "Given the observation that CSTP1 mRNA was decreased in bladder cancer tissues, we presumed that CSTP1 may function as a tumor suppressor in bladder cancers." (PMID 23799035, 2013). "Results of Northern blot shown a moderate expression level of CSTP1 mRNA in SV-HUC1 cells, but in RT4, EJ and T24 bladder cancer cells, CSTP1 mRNA could hardly be detected." (PMID 23799035, 2013). "CSTP1 expression was selectively reduced in bladder cancer tissues and its expression level is positively correlated to the recurrence-free survival of patients with Ta and T1(non-invasive) bladder cancers, and may serve as a prognostic marker for non-muscle invasive bladder cancers." (PMID 23799035, 2013). "Expression profile analysis revealed that CSTP1 mRNA was selectively decreased in non-invasive bladder cancer tissues, suggesting that CSTP1 plays an important role mainly in bladder carcinogenesis, and it may be used as a potential target for bladder cancer treatment." (PMID 23799035, 2013). "We then determined the expression level of CSTP1 mRNA by Northern blot in bladder cancer cell lines and SV-HUC1, a non-transformed urothelial cells." (PMID 23799035, 2013).
renal carcinoma (1 paper, 2013). A carcinoma arising from the epithelium of the renal parenchyma or the renal pelvis. "We first examined CSTP1 mRNA expression level in several kinds of human cancers, including liver, pancreas, stomach, colon, bladder and renal cancers." (PMID 23799035, 2013).
tumor (3 papers, 2013 to 2026). "CPPED1, also known as CSTP1, has been reported to be involved in blocking the cell cycle, promoting apoptosis, and suppressing tumor growth as a potential tumor suppressor." (PMID 30918060, 2019). "Results indicated that, in athymic mice receiving the EJ cells overexpressing CSTP1, tumor growth was significantly suppressed(∼50%), but in athymic mice receiving EJ cells overexpressing CSTP1 ΔPP2Ac, tumor growth almost did not change compared to the control group." (PMID 23799035, 2013). "Taken together, we have identified a novel protein phosphatase targeting Akt protein kinase, CSTP1, which dephosphorylates the hydrophobic motif of Akt specifically at the Ser473 site, blocks cell cycle progression, promotes cell apoptosis and suppresses tumor growth in nude mice." (PMID 23799035, 2013). "Additionally, genes involved in the cellular response to stress were commonly upregulated in tumor C1 and C2 NK cells (HSP90AA1, HSPA1B, HSPH1, DNAJB1, PSMB9, CSTP1)." (PMID 41082397, 2026).
cancer (1 paper, 2013). A tumor composed of atypical neoplastic, often pleomorphic cells that invade other tissues. "CSTP1 gene was first identified by Bai GQ in 2005, which was transactived by complete S protein of hepatitis B virus, and we supposed it may be associated with human cancers." (PMID 23799035, 2013). "Signaling pathways that usually involved in cancer biology, cell cycle control or cell proliferation were examined in CSTP1-overexpressing EJ cells by analysis of luciferase activity using Cignal Reporter Assay Kit." (PMID 23799035, 2013).